INS (insulin)
Diseases named in the same sentence as INS in open-access papers (continued):
Sharing a sentence is not in itself a finding about the gene and the disease.
Insulin resistance (continued). "Insulin levels could be increased due to insulin resistance or a compensation for increased blood glucose in the sweetener groups." (PMID 35268062, 2022). "Considering that insulin is a neurotrophic factor responsible for neuronal growth, survival, and differentiation, it is possible that disruption of insulin signaling due to insulin resistance contributed to the pathogenesis of PN." (PMID 35651981, 2022). "Insulin resistance is one of the main players in the pathophysiology of MetS, in which the target tissue exhibits a subnormal coordinated glucose-lowering response at normal plasma insulin levels." (PMID 36452893, 2022). "Studies have shown that the abundance of Subdoligranulum is positively correlated with microbial richness and HDL-cholesterol levels, and negatively correlated with fat mass, adipocyte diameter, insulin resistance, leptin, insulin, CRP, and IL6 levels in people and animals." (PMID 36611702, 2022). "Regular, moderate physical activity improves the basic metabolism and maximum oxygen intake, which improves long-term metabolic efficiency and capacity, consequently reducing the blood serum concentration of insulin and insulin resistance and stimulating the synthesis of adiponectin." (PMID 35743146, 2022). "Increased concentrations of TNF-α have been shown to induce insulin resistance by increasing phosphorylation of the insulin signaling pathway in animal and cell models, although the administration of anti-TNF-α mAbs had little effect in patients with type 2 diabetes." (PMID 36548717, 2022). "The metabolic markers found to best illustrate NAFLD are: high BMI and abdominal fat, insulin resistance, and increased blood insulin, HbA1c, triglycerides, transaminases, GT, ferritin, creatinine, and uric acid levels, in contrast to a reduction in serum HDL cholesterol." (PMID 36159489, 2022). "The proper nutrition of children after birth causes a rapid increase in the insulin and IGF-1 levels, which may result in a rapid weight gain, insulin resistance, and T2DM in adulthood (referred to a as the catch-up growth hypothesis)." (PMID 35197931, 2022). "Type 2 diabetes is characterized by insulin resistance and defective insulin secretion." (PMID 35159354, 2022). "In obese mice, anthocyanin-loaded niosomes ameliorated insulin resistance and glucose intolerance by reducing plasma insulin, glucose level, leptin, and total cholesterol, indicating the beneficial effects on the reversal of metabolic abnormalities associated with obesity." (PMID 36355516, 2022). "In addition, we have recently demonstrated that mice lacking a variant of the bumetanide-sensitive Nkcc2 (Nkcc2a, Slc12a1v1) exhibit abnormal insulin responses to glucose and develop hyperglycemia, glucose intolerance and insulin resistance." (PMID 36580474, 2022). "Mechanistic understanding of how insulin increases glucose uptake into muscle fibers may therefore help prevent/treat muscle insulin‐resistance." (PMID 35224890, 2022). "Of note, long-term high-calorie diet treatment is capable of stimulating severe insulin resistance in the liver, where the normal function of insulin to regulate glucose metabolism is inhibited, however, the effect of insulin to promote adipogenesis is fully preserved." (PMID 35217669, 2022). "Here, we have demonstrated in a cross-sectional analysis that microbial communities differ by race and insulin sensitivity status, suggesting a role of gut bacteria in the pathogenesis of insulin resistance development in women of different race and ethnicities." (PMID 35045086, 2022). "Patients with compensated liver cirrhosis may have a higher insulin requirement because of the prominent insulin resistance." (PMID 35252271, 2022). "Similarly, high levels of self-reported sedentary behaviour including ST were associated with an increased risk of elevated systolic and diastolic blood pressure, higher glycated haemoglobin (HbA1C), fasting insulin, insulin resistance, and MetS." (PMID 35312701, 2022).
Insulin resistance (continued). "Energy restriction on 2 consecutive days/week, compared with CER, has demonstrated greater reductions in fasting insulin concentration, insulin resistance (homoeostasis model assessment of insulin resistance, HOMA-IR) and fat mass over 3 or 6 months, with comparable energy deficits and weight loss." (PMID 34040199, 2022). "If BCAAs are responsible for insulin resistance, we can imagine that, conversely, a reduction in plasma BCAA concentrations could be associated with an improvement in insulin sensitivity." (PMID 36615726, 2022). "The increased ADM release in adipocytes seems to be a compensatory action attempting to restrain insulin homeostasis rather than a causal factor of insulin resistance thus, type 2 diabetes." (PMID 35681200, 2022). "Furthermore, treatment with parvalbumin blocker significantly lowered insulin levels and ameliorated insulin resistance in HFD-fed mice." (PMID 35676256, 2022). "Yet, increased serum insulin levels, with reduced glucose clearance observed in HF casein group, may be an early indicator of insulin resistance." (PMID 35807769, 2022). "Although insulin resistance and impaired glucose uptake has been observed in liver, ß-cells, and skeletal muscle from rodents, contradictory data obtained from rats showed stimulated insulin/AKT pathway activation through statins." (PMID 35216514, 2022). "Interestingly, glucose only induces insulin resistance in the presence of insulin in cultured hepatocytes, adipocytes and skeletal muscle cells." (PMID 34921686, 2022). "Insulin can stimulate the synthesis of protein and inhibit its degradation, so insulin resistance and/or insufficient secretion may bring about insufficient protein, which will lead to low muscle mass or sarcopenia." (PMID 36274973, 2022). "Insulin resistance adversely affects glycometabolism in insulin-targeted organs and tissues." (PMID 35495935, 2022). "T2D is a chronic inflammatory disease characterized by elevated plasma glucose levels arising from pancreatic β-cell dysfunction and inefficient action of insulin in cells (insulin resistance (IR)) in insulin-sensitive (IS) organs and tissues such as the skeletal muscle, liver or heart." (PMID 35055345, 2022). "In contrast, serum insulin level, systemic lipid peroxidation, and oxidative DNA damages as reflected by homeostatic model assessment of insulin resistance and 24-hour-urinary 8-OH-dG concentrations, as well as urinary isoprostane significantly decreased upon AdipoRon treatment." (PMID 35351872, 2022). "In one study, a significant alteration in metabolic status was reported after 10 days, including systolic blood pressure, glucose, high density lipoprotein cholesterol, leptin, insulin and insulin resistance, however, changes in FMD were only seen after 6 months." (PMID 35887817, 2022). "Insulin resistance thus may represent a state of ‘anabolic resistance’ in skeletal muscle, wherein the insulin-mediated suppression of muscle breakdown is inhibited, potentially leading to increased proteolysis that may eventually result in sarcopenia." (PMID 35147511, 2022). "We hypothesized that HbA1c which reflects average blood glucose levels from the last 8–12 weeks may be a better predictor of an individual’s perceived age than levels of fasting glucose, insulin or HOMA-IR (Homeostatic Model Assessment of Insulin Resistance)." (PMID 35710822, 2022). "Amylin deposition contributes to insulin resistance and oxidative stress being responsible for the development of type II diabetes mellitus (T2DM) by forming toxic amyloid aggregates leading to β-cell mass loss and subsequent reduction in insulin secretion." (PMID 35213966, 2022). "The accumulation of hepatic triglyceride, however, may reduce insulin clearance and result in peripheral insulin resistance." (PMID 36618709, 2022).
Insulin resistance (continued). "In the setting of insulin resistance, insulin's stimulation of NO biological activity is reduced, that is, endothelial cell NO synthase activation is reduced, NO destruction is increased, vasoconstriction is caused, blood pressure is increased, and stroke progression is accelerated." (PMID 35242879, 2022). "Consistent with previous studies, male mice fed HFD for 16 weeks presented with obesity, hyperglycemia, glucose intolerance, insulin resistance, defective glucose-stimulated insulin release (GSIS), and changes in islet gene expression such as Ins1, Ins2 and Gck, as expected." (PMID 35813647, 2022). "The association of metabolic flexibility with mitochondrial function and its lack of association with insulin sensitivity indicate that mitochondria are responsible for the diminished insulin-stimulated increase in the oxidation of substrates in subjects with insulin-resistance." (PMID 36012137, 2022). "Both C57BL/6J and C57BL/6N are prone to DIO, which is manifested by a marked increase in body mass, impaired glucose tolerance, an increase in fasting blood glucose and serum insulin that develops later in C57BL/6J than C57BL/6N, decreased insulin release, and insulin resistance." (PMID 35399951, 2022). "Moreover, insulin-stimulated glucose oxidation and insulin inhibition of lipid oxidation are impaired in subjects with insulin resistance and T2D." (PMID 36876056, 2022). "Insulin resistance is due to decreased suppressive effect of insulin on hepatic glucose production." (PMID 36654578, 2022). "This may be due to a longer time period of training being required and/or due to improvements in insulin sensitivity being more pronounced in subjects with existing insulin resistance." (PMID 35761262, 2022). "The distribution of the clusters suggests that deficient insulin secretion, rather than the often-purported insulin resistance, is the driver of young-onset type 2 diabetes in India." (PMID 34689214, 2022). "The observation that L. johnsonii NVs increased insulin secretion only at high glucose levels shows that NVs may potentially have a protective effect against insulin resistance and in type 2 diabetes metabolic syndrome." (PMID 35757772, 2022). "It has been suggested that AN shares genetic variation with various metabolic phenotypes, including fasting insulin, leptin, insulin resistance, type 2 diabetes, and HDL cholesterol, which may be independent of BMI." (PMID 35013117, 2022). "Thus, insulin resistance and altered insulin signaling can induce metabolic abnormalities and the occurrence of AD." (PMID 35457168, 2022). "SAP and TERP decreased glucose and insulin, which may indicate mitigation of insulin resistance in a metabolic model." (PMID 35684317, 2022). "Early AAM was found to be associated with the rising trend of HDL but lower diastolic blood pressure (DBP) combined with lower levels of TGs, log fasting insulin, log homeostasis model assessment of insulin resistance (HOMA-IR), and log homeostasis model assessment of β cell function (HOMA-β)." (PMID 35548428, 2022). "The commonly used term “insulin” could refer not only to pharmacotherapy, but also to clinical conditions such as insulin resistance or even to laboratory tests." (PMID 35924057, 2022). "Obesity also leads to impaired insulin signaling and subsequent insulin resistance." (PMID 36143440, 2022). "The compensatory downregulation could also extend beyond muscle atrophy into insulin signaling as insulin resistance is a common observation during critical illness and high myostatin levels have also been associated with insulin resistance." (PMID 35922829, 2022). "Again, when insulin signaling is impaired it results in insulin resistance." (PMID 36355096, 2022). "This can be explained on the basis of the hypothesis that such a phenomenon developed as a compensatory response to impaired insulin action, thereby confirming that the plasma visfatin levels were a consequence of the degree of insulin resistance." (PMID 35629157, 2022).
Insulin resistance (continued). "In a study of 32 Hispanic children (38% female, BMI ≥85th percentile), regression analyses indicated that VAT was associated with greater fasting insulin, lower insulin sensitivity, and greater insulin resistance, independent of total fat mass." (PMID 36172390, 2022). "Given that insulin resistance is a major feature of MetS, reduced insulin action in the bladder mucosa could be a common mechanism for eliciting OAB symptoms under circumstances, such as those of MetS." (PMID 36009505, 2022). "Insulin resistance is a key characteristic of type 2 diabetes (T2D), and alterations in insulin sensitivity may occur even decades before the clinical onset of T2D." (PMID 36288097, 2022). "In another parallel randomized clinical trial, daily drinking of 240 mL soy milk as a part of low-calorie diet for eight weeks significantly reduced serum ALT, hs-CRP, and insulin, and improved insulin resistance, and systolic and diastolic blood pressure in the NAFLD patients (n = 70)." (PMID 35678936, 2022). "Importantly, hepatic DNP concentrations (~5 μM) were sufficient to protect aging HFD‐fed mice from hepatic insulin resistance, as insulin‐mediated suppression of endogenous glucose production (EGP) was significantly increased." (PMID 35088525, 2022). "Osteocalcin could increase β cell proliferation, improve insulin expression, and regulate peripheral insulin resistance via adiponectin, an adipocyte-specific insulin-sensitizing hormone." (PMID 36601005, 2022). "This is consistent with findings from murine models, which suggest maternal FA intake is associated with adverse metabolic outcomes in the offspring, specifically adipocyte morphology, glucose intolerance and insulin resistance, and impaired insulin synthesis and fat metabolism." (PMID 36235580, 2022). "Three months old growth restricted F1 rats developed hepatic insulin resistance, which was represented by its impaired insulin function in controlling the hepatic glucose production (HGP) important for maintaining blood glucose equilibrium (1.6 times higher HGP in IUGR rats compared to the control)." (PMID 35432208, 2022). "At the brain level, insulin resistance is proposed to lead to impaired neurotransmitter release, altered neuronal and glial cell receptor regulation, or homeostatic and inflammatory responses to insulin." (PMID 36368970, 2022). "Given its insulin-sensitizing properties, metformin may also have the ability to help with glycemic control during puberty when insulin resistance worsens and many youth with type 1 diabetes fail to meet clinical guidelines." (PMID 36992735, 2022). "The most parsimonious explanation is that with lowering of insulin resistance (and thereby improving insulin sensitivity), glucose disposal could be achieved with less insulin, and this reduced β-cell overactivity." (PMID 35052658, 2022). "Specifically, the amylin to insulin ratio was higher when the beta-cell damage was more extensive (i.e., when a higher streptozotocin dose had been used) or when moderate beta-cell damage occurred in combination with insulin resistance." (PMID 35456307, 2022). "GDM is defined as a disorder of glucose tolerance and carbohydrate intolerance, which first begins or is diagnosed during pregnancy and is associated with symptoms such as high blood glucose, increased insulin resistance, decreased insulin sensitivity, and increased insulin requirements." (PMID 35794663, 2022). "Thus, only the DHEA group displayed significant and stabilized increases in FINS, HOMA-IR and postprandial insulin levels, indicating hyperinsulinemia and insulin resistance in the DHEA group." (PMID 36619569, 2022). "It is defined by peripheral insulin resistance and insulin secretion abnormalities." (PMID 36557843, 2022). "Severe high glucose could promote dephosphorylation of IRE1α, resulting in the attenuation of IRE1α activity and insulin resistance or reduced insulin production." (PMID 35844917, 2022).
Insulin resistance (continued). "Inhibition of PTP1B activity might improve IR and IRS, leading to the improvement of insulin resistance and enhancement of insulin sensitivity." (PMID 35056765, 2022). "All these data support the hypothesis that irisin may be a compensatory mechanism to offset HFD/obesity-induced insulin resistance by increasing energy expenditure and insulin secretion to prevent diabetes." (PMID 35628332, 2022). "Insulin resistance was induced by treating IHH cells with high levels of insulin." (PMID 36072934, 2022). "We proposed that every individual could be characterized by a given DI which would determine the insulin response that would characterize their beta cell compensation for a given level of insulin resistance." (PMID 35163746, 2022). "Previously, Bamford and colleagues suggested that chronic increases in the release of GLP-1 in ponies and Andalusian horses may lead to increased insulin secretion and insulin resistance." (PMID 35906619, 2022). "We assessed the inter- and intra-individual differences in glucose, insulin, and C-peptide concentrations during 5-h oral glucose tolerance tests (OGTTs); the surrogate markers of insulin resistance (HOMA-IR and Matsuda index); and beta-cell function (distribution index and insulinogenic index)." (PMID 36557270, 2022). "A 3-DG may induce hepatic insulin resistance by decreasing the insulin-induced expression of GLUT2, the insulin-stimulated tyrosine phosphorylation of IRS-1, and the expression of the downstream target proteins." (PMID 36432614, 2022). "There is evidence that excessive visceral fat accumulation, manifested as central obesity, can impair insulin sensitivity and even result in insulin resistance, and reduced insulin sensitivity interferes with leptin signaling, which plays in important role in puberty initiation." (PMID 35846287, 2022). "In this context, NF-κB is a transcription factor that regulates expression of many kinds of cytokines and inflammatory proteins in oxidative environments, and the increased NF-κB signaling decreases insulin action and promotes insulin resistance in the liver and whole body." (PMID 35629342, 2022). "We hypothesize that in a proportion of BD patients insulin resistance acts as a chronic stressor leading to impairment of PI3K/Akt insulin signaling in the brain." (PMID 36038539, 2022). "Our results suggest that oxidative stress-induced o- and m-Tyr could incorporate into cellular proteins, interfere with insulin signaling, inhibit glucose uptake, and thus induce chronic insulin resistance." (PMID 35625712, 2022). "Also, in the diabetic subject, thiazide diuretics even at lower doses also increase insulin resistance and decrease insulin release." (PMID 35967126, 2022). "In skeletal muscles, several conditions may contribute to insulin resistance, including disorders of the insulin signal, glucose transport, glucose phosphorylation, glycogen synthesis and the oxidative activity of mitochondria." (PMID 35846491, 2022). "Stress-induced hyperglycemia (SIH) is defined as temporary insulin-resistance associated with increased production of glucose and lack of sufficient insulin secretion in non-diabetic patients." (PMID 35178208, 2022). "This may also serve as a compensatory mechanism for developed insulin resistance by bypassing suppression of insulin-mediated activation of the PI3K/Akt pathway." (PMID 35742902, 2022). "Insulin resistance (IR) is defined as an impaired biologic response to glucose disposal and insulin stimulation of target tissues (mainly the liver, muscle, and adipose tissue), leading to a compensatory increase in beta-cell insulin production and hyperinsulinemia." (PMID 35185617, 2022). "Previous evidence showed that increased oxidative stress exacerbates insulin resistance by impairing the secretion of insulin by β-cells; however, RPG supplementation to the same cows used in this study elicited a positive response in circulating insulin concentration before feeding." (PMID 35326119, 2022).